NTRK1 (neurotrophic receptor tyrosine kinase 1)
Diseases named in the same sentence as NTRK1 in open-access papers (continued):
Sharing a sentence is not in itself a finding about the gene and the disease.
neuroblastoma (continued). "The SY5Y neuroblastoma cell line was stably transfected with NTRK1, NTRK2 or a vector control to generate these models, designated SY5Y-NTRK1, SY5Y-NTRK2 and SY5Y-vec, respectively." (PMID 25361003, 2014). "Here we demonstrate that NRG1 is also a predominant effector molecule of NTRK1-expressing neuroblastoma cells regulating communication with Schwann cells." (PMID 25361003, 2014). "SC-conditioned medium activated the NTRK1 receptor in a neuroblastoma cell culture model conditionally expressing NTRK1 and induced differentiation markers in NTRK1-expressing cells." (PMID 25361003, 2014). "Our study provides strong evidence that NTRK1-expressing neuroblastoma cells both attract and stimulate the proliferation of adjacent Schwann cells by secreting NRG1, which in turn leads to NGF-mediated differentiation of neuroblastic cells." (PMID 25361003, 2014). "Since NRG1 has previously been demonstrated to also be essential for Schwann cell migration, we next examined the impact of NTRK1-expressing neuroblastoma cells on the migratory activity of Schwann cells." (PMID 25361003, 2014). "Reanalyses of data from exon resolution mRNA arrays previously obtained from 101 primary neuroblastomas demonstrated a highly significant positive correlation between NTRK1 and NRG1 expression in vivo." (PMID 25361003, 2014). "NTRK1 induction in neuroblastoma xenografts mixed with primary SC also significantly reduced tumor growth in vivo." (PMID 25361003, 2014). "NRG1, expressed and secreted by NTRK1-positive SY5Y neuroblastoma cells, was identified as a chemokine and a major mediator of mitogenic effects in Schwann cells." (PMID 25361003, 2014). "We have recently shown that cross-talk between neuroblastoma and immune effector cells is significantly influenced by expression of NTRK1." (PMID 25361003, 2014). "Media conditioned by NTRK1-expressing neuroblastoma cells induced SC proliferation and migration, while antibody-based NRG1 neutralization significantly decreased these effects." (PMID 25361003, 2014). "We assessed the potential interaction of NTRK1-expressing neuroblastoma cells with Schwann cells in an in vivo experiment using a xenograft model of SY5Y cells in nude mice." (PMID 25361003, 2014). "As a first step to examine interactions between NTRK1-expressing neuroblastoma cells with stromal cells of the peripheral nervous system, we reanalyzed gene expression data previously obtained from the neurotrophin recepter-expressing SY5Y cell culture model." (PMID 25361003, 2014). "High expression of NTRK1 is present in neuroblastomas with favourable biological features and highly correlated with patient survival." (PMID 17531100, 2007). "NTRK1 may play a pivotal role in spontaneous regression of stage 4S neuroblastoma through both the induction of the NGF-dependent neuronal differentiation and the enhancement of the immune response." (PMID 41189817, 2025). "SH-SY5Y neuroblastoma cells express undetectable NTRK1 levels." (PMID 38398114, 2024). "NTRK1 decreases malignancy and/or spontaneous degeneration of neuroblastoma cells." (PMID 36975521, 2023). "Moreover, an NTRK1 splice variant, TRKA III, and an in-frame deletion mutant (ΔTRKA) were reported in neuroblastoma and acute myeloid leukemia, showing their tumorigenicity." (PMID 37212982, 2023). "In this regard, low-risk neuroblastoma is common in younger children with <18 months of age at the time of diagnosis and NTRK1 expression (encoding TRKA) is a strong prognostic histological marker for favorable cases, whereas TRKB (encoded by NTRK2) is associated with poor outcome." (PMID 34493726, 2021). "It is tempting to speculate that the impaired G2/M checkpoint could at least in part explain the genomic instability frequently observed in primary TrkA/NTRK1 expressing neuroblastoma." (PMID 34885133, 2021). "However, a decreased mRNA expression of NTRK1 was found and attributed to the methylated promoter in neuroblastoma and ovarian cancer." (PMID 33593392, 2021).
neuroblastoma (continued). "NTRK1 promoted proliferation and metastasis of cancer cells and lead to poor prognosis in multiple cancers, while it suppressed cell proliferation in neuroblastoma." (PMID 33593392, 2021). "Moreover, an NTRK1 splice variant, TRKA III, and an inframe deletion mutant (ΔTRKA) were reported in neuroblastoma and acute myeloid leukemia." (PMID 31974683, 2020). "NTRK1 genetic variants occur in tumors of neuronal type (neuroblastoma and medulloblastoma), but also in non-neuronal cancers, like thyroid, breast, lung, prostate, ESCC, PDAC, GC, HC, and CRC." (PMID 31812953, 2019). "Finally, neurotrophic tyrosine kinase 1 (NTRK1, TrkA), is a well-known neuroblastoma antigen that binds nerve growth factor, and whose expression has been associated with a number of human cancers, often being discovered as an oncogenic fusion protein." (PMID 28871274, 2017). "The combined treatment increased the amount of neurite outgrowths as well as neurite length in neuroblastoma cell lines and increased the expression of neurofilament, as well as NTRK1." (PMID 25695609, 2015). "NRG1 expression was restricted to cell lysates of NTRK1-positive neuroblastoma cells." (PMID 25361003, 2014). "The authors continued to presume that the NGF/NTRK1 interaction contributed to differentiation in vivo, since defects in the NTRK1 receptor pathway of the employed cell lines hampered comparison with processes in less aggressive maturing neuroblastomas." (PMID 25361003, 2014). "Finally, we assessed the effects of NTRK1 expression in neuroblastoma cells on neuroblastic tumor progression in the presence of Schwann cells in vivo." (PMID 25361003, 2014). "NTRK1 was reported to be a favorable neuroblastoma (NB) genes." (PMID 21989042, 2011). "NTRK1 c.1810C>T polymorphism appears to be a new independent prognostic factor of poor outcome in neuroblastoma, especially in children under 18 months of age with no MYCN amplification." (PMID 20003389, 2009). "Studies have shown that the upregulation of regular NTRK1 isoforms (TrkAI/II) in normoxia condition will have a good prognosis in neuroblastoma (NB), so it plays an antioncogenic role in NB." (PMID 35627227, 2022). "Notably, NTRK1 amplification and subsequent TrkA overexpression is more common than NTRK1 rearrangement and has been reported in a variety of cancers including breast, neuroblastoma, lung cancers, pancreas, ovary, and others." (PMID 35707464, 2022). "As current therapeutic regimens of NB also include radiotherapy, we here evaluated the response of neuroblastoma cells to IR as a function of TrkA/NTRK1 expression, which is a master regulator of NB biology." (PMID 34885133, 2021). "Based on our in vitro findings demonstrating that NTRK1-expressing neuroblastoma cells attract Schwann cells which, in turn, induce differentiation of the neuroblastic cells, we postulate that this constellation properly reflects the in vivo situation of biologically favorable neuroblastomas." (PMID 25361003, 2014). "Taken together, these data show that NTRK1 expression causes upregulation and secretion of the Schwann cell-stimulating factor, NRG1, in vitro and is strongly correlated with NRG1 expression in vivo, suggesting a potential role for NTRK1 in the tumor-stroma dialog in neuroblastoma." (PMID 25361003, 2014). "To confirm that the changes in gene expression observed in neuroblastoma cells treated with STM2457 were due to targeting METTL3, we analyzed CHGA and NTRK1 mRNA levels in control SK-N-BE2 cells and cells engineered to overexpress METTL3." (PMID 38691450, 2024).
neuroblastoma (continued). "Western blot analysis demonstrated that STM2457 treatment increased the levels of TRKA, the protein product of NTRK1, in Kelly and NGP neuroblastoma cells." (PMID 38691450, 2024). "NTRK1 and its activation by nerve growth factor (NGF) have been shown to induce differentiation and increase the immunogenicity of human neuroblastoma cells." (PMID 34771457, 2021). "The impact of NTRK1 activation on the proteome and the phosphoproteome was delineated using the MYCN-amplified neuroblastoma cell line, IMR5." (PMID 34771457, 2021). "For example, the expression footprint of six neuroblastoma-related genes (ALK, BIRC5, CCND1, MYCN, NTRK1 and PHOX2B) have been used to differentiate neuroblastoma molecular subtypes." (PMID 34842635, 2021). "In NTRK1-expressing cells, however, we observed a translocation of LMNA to the nucleus where it was localized within intra-nuclear aggregates in the four neuroblastoma cell lines analyzed: IMR5, SH-SY5Y, NGP and SKNAS." (PMID 34771457, 2021). "The inducible expression of NTRK1/TrkA and its activation via NGF were realized and validated in four established human neuroblastoma cell lines, NGP, IMR5, SKNAS and SH-SY5Y." (PMID 34771457, 2021). "Similar to NTRK1, NTRK3 has been demonstrated to be an oncogene in breast cancer and gastric cancer, but it acts as a tumor suppressor gene in CRC, neuroblastomas, and head and neck squamous cell carcinoma." (PMID 33593392, 2021). "MYCN and NTRK1 exert opposing functions in neuroblastoma (NB)." (PMID 34771457, 2021). "We therefore established inducible TrkA/NTRK1 expression in two human neuroblastoma cell lines, SY5Y and Kelly, to dissect the impact of TrkA/NTRK1 on cell cycle regulation and checkpoint responses." (PMID 34885133, 2021). "NTRK1/TrkA expression and MYCN amplification are hallmarks of excellent and dismal outcome, respectively, in childhood neuroblastomas (NBs)." (PMID 34771457, 2021). "Analysis of genes that are increased with retinoic acid induced differentiation of neuroblastoma cells (NGRF, NF68, NTRK1, SYP, MAP2, NEFM, DKK2) showed that all were elevated after 72 hours Wnt3a/Rspo2 treatment." (PMID 29505958, 2018). "We have previously demonstrated that HDAC8 depletion of neuroblastoma cells via siRNA transfections resulted in an upregulation of markers for differentiation (NEF and NTRK1) as well as G0/G1 cell cycle arrest with p21WAF1/CIP1 upregulation." (PMID 25695609, 2015). "Overall, our data demonstrate that progression of neuroblastoma growth in vivo may be delayed by simultaneously mimicking the most prominent genetic and histological hallmarks of neuroblastic tumors with favorable prognosis, NTRK1 expression and presence of Schwann cells." (PMID 25361003, 2014). "Schwann cells were previously reported to express and secrete the NTRK1-specific ligand, NGF, which lead to peripheral nerve regeneration and axonal myelination as well as to neuroblastoma cell differentiation." (PMID 25361003, 2014). "Reanalysis of microarray data from human SY5Y neuroblastoma cells stably transfected with either NTRK1 or NTRK2 revealed upregulation of the mRNA for the SC growth factor, NRG1, in NTRK1-positive cells." (PMID 25361003, 2014). "Previous research on neuroblastoma cells (SH-SY5Y) has shown that I2 can have neuro-differentiating effects by increasing the number of neurites and inducing the expression of neural NE markers such as NTRK1." (PMID 40869121, 2025). "We surveyed our seven neuroblastoma cell lines for NTRK1,2,3 expression and demonstrated enhanced mRNA levels for NTRK2 and NTRK3 in all tested cell lines, as well as enhanced NTRK1 expression in 5 of 7 experimental cell lines." (PMID 29207623, 2017). "In consequence, NTRK1-expressing subclones have previously been demonstrated to downregulate NTRK1 expression or to be overgrown by neuroblastoma cells not expressing NRTK1 in the in vivo setting." (PMID 25361003, 2014).
neuroblastoma (continued). "Our observations of only marginal neurite outgrowth in neuroblastoma cells without NTRK1 activation are consistent with these reports." (PMID 25361003, 2014). "Mutual interaction of NTRK1-expressing neuroblastomas with Schwann cells via the NRG1/NGF-axis helps to explain both the high Schwann cell infiltration in NTRK1-positive primary neuroblastomas and the absence of Schwann cells in NTRK1-negative neuroblastomas." (PMID 25361003, 2014). "While the data presented here indicate that NTRK1 expression and activation also interfere with LMNA-S22 phosphorylation and nuclear lamina organization, it will require further work to dissect the impact of kinase-mediated LMNA phosphorylation on replication in neuroblastoma cells." (PMID 34771457, 2021). "According to our proposed model of bidirectional interaction, this might explain the diminished content of vital glia within the mixed-cell xenografts, since the Schwann cell effector molecule, NRG1, is not secreted by NTRK1-negative neuroblastoma cells." (PMID 25361003, 2014). "Indeed, NTRK1 expression was no longer detected in mixed neuroblastoma-Schwann cell xenografts at the end of our in vivo experiment (data not shown)." (PMID 25361003, 2014).
breast cancer (114 papers, 2006 to 2025). A primary or metastatic malignant neoplasm involving the breast. "Of note, NTRK1 overexpression has been linked with CNS metastasis in breast cancer." (PMID 35572973, 2022). "One patient with PTC and other two malignancies (sigmoid colon cancer diagnosed before TC and breast cancer diagnosed after TC), harboring TPM3/NTRK1 and TERT C228T mutations in PTC, underwent chemotherapy treatment and subsequently died." (PMID 33923728, 2021). "Potentially actionable molecular alterations include agnostic targets (NTRK1-2-3, RET fusions, BRAF V600E mutations, microsatellite instability, high tumor mutational burden), or tissue-specific targets, such as EGFR mutation in NSCLC or PIK3CA mutations in breast cancer." (PMID 39766151, 2024). "Three non-recurrent NTRK1 fusions were each detected in two cases of lung cancer (SQSTM1-NTRK1 and IRF2BP2-NTRK1) and one case of breast cancer (EFNA1-NTRK1)." (PMID 36369474, 2022). "Fusion partners of FGFR2 reported specifically in breast cancer are AFF3, CASP7 and CCDC6, while partners identified in other cancers include TACC and KIAA family members, PPHLN1, NTRK1, BICC1, AHCYL1, OFD1 and SLC45A3." (PMID 34344433, 2021). "Nevertheless, similar findings from other oncological fields support the relevance of this issue, as for example in breast cancer the formation of NGF and NTRK1 autocrine axis was evidenced as well." (PMID 29904026, 2018). "However, the successful approval of TKIs to treat ROS1-, RET-, NTRK1-, PDGFR-α, and AXL-rearranged NSCLC is vitally important as it sets the example for approval of TKIs to treat the same RTK-rearranged common epithelial tumors such as colon, gastric, and breast cancers." (PMID 24744988, 2014).
lung cancer (82 papers, 2013 to 2025). A malignant neoplasm involving the lung. "New gene fusions such as those leading to the constitutive activation of the tropomyosin receptor kinase TrkA encoded by the NTRK1 gene have been identified in lung cancer patients." (PMID 31134126, 2019). "NTRK1 (Neurotrophic Receptor Tyrosine Kinase 1; encodes TrkA) was previously reported to impose oncogenic activity in lung cancer cells by fusing with CD74 and, independently, with MPRIP." (PMID 29568375, 2018). "Here, we present the initial instance of a non‐small cell lung cancer (NSCLC) patient with an EGFR mutation who also harbored both NTRK1 and ZRSR2 mutations, which are recognized as significant factors in the development of primary resistance to Osimertinib through further validation." (PMID 39907312, 2025). "Mutations of gene NTRK1 were also reported in lung cancer, while the probable mechanism how these mutations excluding Rearrangement mutation contributed to lung cancer progression was still unknown." (PMID 36531058, 2022). "EML4-ALK fusions, RET rearrangements, ROS1 fusions, and NTRK1/2/3 fusions are observed at a cumulative frequency of 3 %–10 % in lung cancers." (PMID 40503459, 2025). "The discovery of therapeutically targetable gene fusions, such as ALK, RET, ROS1, and NTRK1, has significantly advanced lung cancer management." (PMID 39810398, 2025). "We looked at the distribution of breakpoints in ALK, RET, ROS1, NTRK1, as well as other kinase genes known to generate oncogenic fusions in lung cancer, such as EGFR, ERBB4, MET, FGFR3, and EPHA245." (PMID 38877018, 2024). "Fusions of the NTRK1 gene are found in lung cancers, colorectal and thyroid cancers, and Glioma, etc." (PMID 37188172, 2023). "Several fusion partner genes of NTRK1 were reported in the past few years in thyroid cancer, glioblastoma and lung cancer." (PMID 36531058, 2022). "In recent years, NTRK1 rearrangements have been confirmed in multiple cancers by next-generation sequencing, including lung cancer, soft tissue sarcoma, glioma, and malignant melanoma." (PMID 35707464, 2022). "With the development of multi-omics data analysis tools and sequencing methods, NTRK1 gene fusions have been found in colorectal cancer, glioma, and lung cancer." (PMID 35707464, 2022). "Mutations in NTRK1 and DDR2, which encode tyrosine kinase receptors, have been reported in lung cancer." (PMID 36499051, 2022). "Recently in lung cancer, two different gene fusions involving the NTRK1 gene were observed with the synthesis of constitutive TrkA tyrosine kinase domain activation." (PMID 36289793, 2022). "In a mouse model of KP mutant lung cancer, neurotrophic tyrosine receptor kinase 1 (NTRK1) expression increased significantly after treatment with a PD-1 inhibitor, and NTRK1 promoted abnormal JAK1 and STAT3 activation." (PMID 32000802, 2020). "Evidence from lung cancer models, in which NTRK1 activity has been shown to inhibit the effect of CPIs via several mechanisms, including the promotion of T-cell exhaustion, offer some rational for some interaction between the two pathways." (PMID 33315984, 2020). "Molecular studies revealed that Ntrk1 regulates KP lung cancer cell intrinsic biological processes such as cell signaling to AKT and MAPK to promote cellular growth as well as regulation of in vitro invasive capacity." (PMID 30986992, 2019).